CCL2 (C-C motif chemokine ligand 2)
Diseases named in the same sentence as CCL2 in open-access papers (continued):
Sharing a sentence is not in itself a finding about the gene and the disease.
tauopathy (7 papers, 2019 to 2026). Neurodegenerative disorders involving deposition of abnormal tau protein isoforms (tau proteins) in neurons and glial cells in the brain. "Altogether, our results suggest that the CCR2/CCL2 axis is an important player in brain-immune communication, needed for modifying tauopathy." (PMID 34172073, 2021). "The CCR2/CCL2 axis is required to modify pathology using PD-L1 blockade in a mouse model of tauopathy." (PMID 34172073, 2021). "Altogether our data show for the first time that cerebral overexpression of CCL2 facilitates tau accumulation together with glial neuroinflammatory changes in a relevant mouse model of tauopathy." (PMID 32508844, 2020). "Altogether our results demonstrate an increase in tau accumulation following CCL2 overexpression in the rTg4510 mouse model of tauopathy together with glia activation, ultimately changing the neuroinflammation milieu." (PMID 32508844, 2020). "Nevertheless, this is the first report linking directly CCL2 overexpression with increased tau pathology, providing important new anti-inflammatory avenues for future therapeutic intervention in AD and related tauopathies." (PMID 32508844, 2020). "In fact, the role of CCL2 in AD has been studied more extensively in amyloid β animal models of AD than in tauopathies and have led to contradictory findings." (PMID 32508844, 2020). "Toward this goal, we investigated the role of CCL2 cerebral overexpression on glial activation and tau pathology in the rTg4510 mouse model of tauopathy." (PMID 32508844, 2020). "Because ofthe role of CCL2 in microglial recruitment and subsequent tauopathy, regulation ofthis signaling pathway may eventually serve as a therapeutic target in order tominimize the degree of chronic inflammation." (PMID 40666430, 2025). "Here, we hypothesized that the C-C chemokine receptor 2 (CCR2)/CCL2 axis might be involved in the therapeutic effect in tauopathy, by facilitating recruitment of CCR2+ monocytes." (PMID 34172073, 2021). "We also can't exclude the possibility of a third and unrelated mechanism that could link CCL2 to induced tauopathy, while microglia activation is a by-product of tau pathology worsening." (PMID 32508844, 2020). "Thus, CCL2 seems to be a viable candidate to glial activation in the neuropathology of AD and other tauopathies." (PMID 32508844, 2020). "Here, we hypothesized that the brain-immune communication pathway that is needed to be activated to combat tauopathy involves monocyte mobilization via the C-C chemokine receptor 2 (CCR2)/CCL2 axis, and additional immune cells, such as CD4+ T cells, including FOXP3+ regulatory CD4+ T cells." (PMID 34172073, 2021).
viral myocarditis (7 papers, 2014 to 2025). Myocarditis that is caused by an infection with a viral agent. "CCL2 incidence in viral myocarditis was even more evident after blocking CCL2 activity in vivo, since those infected mice exhibit reduced myocardial cell infiltration, decreased serum CK-MB levels and increased host survival." (PMID 29375564, 2017).
acute monocytic leukemia (6 papers, 2016 to 2023). Acute monoblastic leukemia (AML-M5), is one of the most common subtypes of acute myeloid leukemia (AML) that is either comprised of more than 80% of monoblasts (AML-M5a) or 30-80% monoblasts with (pro)monocytic differentiation (AML-M5b). "Meanwhile, P. pinaster EO (α-pinene 62%) did not inhibit LPS-indued TNF-α and CCL2 production in human acute monocytic leukemia cells (THP-1)." (PMID 35744988, 2022). "Indeed, our previous data showed that down-regulation of GMD factors UPF1, PNRC2, or GR promotes the chemotaxis of human acute monocytic leukemia cell lines (THP-1 cells) by up-regulating CCL2 mRNA and CCL2 protein." (PMID 27798850, 2016).
airway hyperresponsiveness (6 papers, 2010 to 2024). "It is reported that a number of chemokines such as CCL2, CCL5, CXCL10 are associated with RSV-induced airway hyperresponsiveness and CCL11, CCL17, and CCL 22 are involved in the development of pulmonary eosinophilia with RSV infection." (PMID 21980478, 2011).
bone metastasis (6 papers, 2019 to 2026). Transfer of a neoplasm from its primary site to bones. "Bone metastasis linked with CCL4 (OR = 0.991, p = 0.017) and CCL2 (OR = 0.996, p = 0.001)." (PMID 41957068, 2026). "Additionally, EP4 antagonists can suppress proinflammatory cytokines (e.g., C-C motif chemokine ligand 2 [CCL2], IL-6, and C-X-C chemokine motif 8 [CXCL8]), reduce inflammation-dependent bone metastasis, and diminish immunosuppression, while restoring antitumor immunity (91, –93)." (PMID 34607951, 2021). "However, both PROM1 and CCL2 exerted no significant impacts on the survival of single BRCA bone metastasis patients, which might be due to the insufficient sample size." (PMID 36193308, 2022). "This study identified 74 DEGs between BRCA samples with or without bone metastasis, and 5 important DEGs were finally filtered, namely, MMP9, ITGB3, BMP2, CCL2, and PROM1." (PMID 36193308, 2022).
Chagas disease (6 papers, 2012 to 2025). A parasitic infection caused by Trypanosoma cruzi. "During Trypanosoma cruzi infection, the immune system activates a robust inflammatory response, involving cytokines and chemokines like IFN-γ, TNF, IL-6, IL-1β, CCL2, and CCL5, to control parasite replication." (PMID 40936920, 2025). "Regarding chemokines, CXCL10 and CCL5 were increased in IND and CCC patients compared to CTRL, while CCL2, CXCL9 and CXCL8 were reduced in both clinical forms of Chagas disease compared to CTRL." (PMID 38390336, 2024).
clear-cell renal cell carcinoma (6 papers, 2016 to 2023). "VEGFR1 knockdown inhibits MCP-1 (CCL2) expression of clear cell renal cell carcinoma cells." (PMID 33247124, 2020). "We previously reported that the pVHL‐atypical PKC‐JunB pathway contributed to promotion of cell invasiveness and angiogenesis in clear cell renal cell carcinoma (ccRCC), and we detected chemokine (C‐C motif) ligand‐2 (CCL2) as one of downstream effectors of JunB." (PMID 27666332, 2016). "High expression of MCP-1 and CCR2 were significantly associated with shortened survival time and increased risk of recurrence in patients carrying non-metastatic clear-cell renal cell carcinoma and CCL2/CCR2 signature had a negative effect on overall survival and recurrence-free survival." (PMID 27788494, 2016). "In this study, we aim to determine the prognostic value of CCL2 expression as well as its receptor C-C motif receptor type 2 (CCR2) in patients with non-metastatic clear cell renal cell carcinoma (ccRCC) after surgery." (PMID 27409666, 2016).
crescentic glomerulonephritis (6 papers, 2015 to 2023). A histopathologic term for a pattern of diseases characterized by extensive crescent formation in the glomeruli; patients present clinically with rapid deterioration of renal function, and possible progression to end-stage renal failure within weeks or months. "Likewise, MCP-1/CCL2 neutralizing antibody reduced glomerular macrophage infiltration and decreased crescent formation in experimental rat and murine crescentic glomerulonephritis." (PMID 34307414, 2021).
demyelinating disease (6 papers, 2008 to 2023). A broad group of disorders that affect the myelin sheaths that cover the neurons. "Strategies aimed at reducing CCL2 level could support the treatment of neurodegenerative and demyelinating disorders, as a number of studies indicate that these levels are elevated in the body fluids and tissues of affected patients." (PMID 37765263, 2023). "Previously, the effects of some of these chemokines such as CCL5, CCL9, and CCL2 on the development of TMEV-induced demyelinating disease were reported." (PMID 29410948, 2018).
esophageal cancer (6 papers, 2021 to 2025). A primary or metastatic malignant neoplasm involving the esophagus. "A study on esophageal cancer showed that CCL2 inhibits the recruitment of tumor-associated macrophages and the polarization of type II macrophages." (PMID 38776028, 2024). "Similarly, in esophageal cancer, the expression of IL-33 increased the secretion of CCL2 via NF-κB, and the cancer progresses by recruiting Tregs to the cancer tissue." (PMID 34445235, 2021). "In human esophageal tissue, increased CCL2 promoted canceration through the inflammation of the esophageal mucosa and increased monocyte tissue infiltration throughout disease progression to hyperplasia and esophageal cancer." (PMID 34445235, 2021). "C-C motif chemokine ligand-2 (CCL2), through its receptor CCR2 (which is expressed on the surface of M2 TAMs), upregulates PD-L2 expression in M2 TAMs and reduces CD8 cytotoxic T lymphocyte (CTL)-mediated apoptosis of esophageal cancer cells (ESCCs), thereby causing immune escape in ESCC [+73]." (PMID 36522474, 2023).
Fever (6 papers, 2017 to 2025). Body temperature elevated above the normal range. "We also observed a tendency towards increased MCP-1/CCL2 transcription after warming to pyrexia, though not to significance, that also plays a role in regulating leukocyte trafficking (data not shown)." (PMID 31871429, 2019).
fungal infections (6 papers, 2012 to 2024). "Following fungal infections, monocytes/macrophages are recruited to the site of infection, partially in response to CCL2." (PMID 39585917, 2024). "Importantly, our results are the first report of a central role of the IFN-I-driven CCL2/CCR2 pathway in controlling inflammatory monocyte trafficking during fungal infections." (PMID 22911155, 2012). "Here we demonstrate that Trim72 may protect against fungal infection by enhancing macrophage recruitment through NF-κB and ERK1/2 signaling-mediated increased cell migration and CCL2 generation in macrophages." (PMID 39585917, 2024).
gestational diabetes (6 papers, 2019 to 2025). Carbohydrate intolerance first diagnosed during pregnancy. "The up-regulation of miR-452 in HUVEC from infants of mothers with gestational diabetes might be a defense mechanism to down-regulate TNFα, CCL2, and RETN in HUVEC." (PMID 31013606, 2019).
H1N1 virus infection (6 papers, 2011 to 2024). "Characterization of inflammatory cell types in mice lung showed that overexpression of CCL2 and CCR2+ monocyte-derived cells (monocyte-derived dendritic cells and exudate macrophages) are the predominant cause of immune pathology during PR8/H1N1 virus infection." (PMID 28558796, 2017).
Hypoglycemia (6 papers, 2018 to 2023). A decreased concentration of glucose in the blood. "Furthermore, plasma glucose levels correlated negatively with brain levels of mRNAs encoding TNF-α, IL-1β, IL-6, CCL2 and iNOS, suggesting that hypoglycemia and the expression of these pro-inflammatory markers might be linked." (PMID 30375380, 2018).
ischemic cardiomyopathy (6 papers, 2013 to 2023). Ischemic cardiomyopathy is a cardiomyopathy in which a weakness in the muscle of the heart due to inadequate oxygen delivery to the myocardium with coronary artery disease being the most common cause. "In patients with ischemic cardiomyopathy, polymorphism in CCL2 gene (CCL2-2518 A/G single nucleotide polymorphism) was correlated with C-reactive protein (CRP) level." (PMID 27242392, 2016).
macrophage activation syndrome (6 papers, 2020 to 2024). A complication of rheumatic disease that is caused by excessive activation and uncontrolled proliferation of T lymphocytes and well-differentiated macrophages. "Cytokine storm, defined as macrophage activation syndrome (MAS), is characterized by the release of multiple pro-inflammatory cytokines (IL-1β, IL-18, IL-6, IL-2, IL-7, TNF-α) and chemokines (CCL2, CCL3) from macrophages." (PMID 35008658, 2021). "The cytokine profile in these studies is comparable to that reported in cytokine release syndromes, such as macrophage activation syndrome, which is characterized by increased expression of cytokines (IL6, IL7, and TNF) and inflammatory chemokines (CCL2, CCL7, CXC-10, and CXCL-11)." (PMID 35145507, 2021). "Careful observation revealed that the excessive cytokines and chemokines activated by macrophages (i.e., IL-6, IL-7, TNF-α, CCL-2/MCP-1, CCL-3/MIP-1α) were similar to results previously found in hemophagocytic lymphohistocytosis (HLH) and macrophage activation syndrome (MAS)." (PMID 32922406, 2020).
malignant pleural mesothelioma (6 papers, 2018 to 2023). A malignant neoplasm that arises from mesothelial cells in the pleura and shows a diffuse growth pattern. "In the context of malignant pleural mesotheliomas that secrete high levels of CCL2, CCR2 transduction into meso CAR-T cells increases CCL2-induced calcium flux, cell migration and cell death." (PMID 36419115, 2022). "The results obtained from the experiments conducted with pleural liquids showed that AUC value for CCL2 was 0.7912 to differentiate MPM (malignant pleural mesothelioma) from ADCA (adenocarcinomas) and BPE (benign pleural effusions)." (PMID 30151375, 2018).
mood disorder (6 papers, 2016 to 2024). A cognitive disorder a disturbance in which the person's mood is hypothesized to be the main underlying feature. "Elevated CCL2 serum levels have also been found in patients with BD suggesting an impact of the CCR2/CCL2 axis in mood disorders." (PMID 33921690, 2021). "Pro-inflammatory markers such as IL-6, IL-1β, IFN-α, TNF-α, and MCP-1/CCL2 are increased in the blood and cerebrospinal fluid (CSF) from patients with mood disorders compared to healthy controls when assessed at the baseline and also after exposure to stressors." (PMID 31817800, 2019).
neovascular glaucoma (6 papers, 2018 to 2024). "Also, in the neovascular glaucoma (NVG) patients, increased level of IL-6, IL-8, PDGF, CCL2, and TNF-α in AH were previously reported." (PMID 32117217, 2020).
obstructive uropathy (6 papers, 2013 to 2022). "In pediatric patients with CAKUT, the chemokine CCL2/MCP-1 has been associated with urinary tract obstruction in UPJO, whereas high urinary levels of CXCL8/IL-8 were found in VUR." (PMID 24692841, 2014). "Based on these results, it should be further investigated if urinary measurements of CCL2/MCP-1 would help detecting obstructive uropathies and if high urine levels of CXCL8/IL-8 would indicate the presence of renal scarring in VUR." (PMID 24692841, 2014). "The chemokine CCL2/MCP-1 and the cytokine TGF-β have been frequently associated with urinary tract obstruction in patients with UPJO, whereas high urinary levels of IL-6 and of CXCL8/IL-8 were found in many patients with VUR and correlated to renal scarring and to renal function deterioration." (PMID 24066006, 2013).
papillary thyroid carcinoma (6 papers, 2016 to 2025). "In TC, CCL2 promotes cell migration and is predictive of papillary thyroid carcinoma, highlighting its significance in tumor progression." (PMID 39928612, 2025). "The expression of CCL2 is an independent predictive factor for recurrence of papillary thyroid carcinoma." (PMID 34464477, 2021). "Our finding of a correlation of CCL2 staining with lymph node status supports previous results, as CCL2 expression is correlated with lymph node metastasis in papillary thyroid carcinoma." (PMID 32429318, 2020). "To further validate our results we investigated the effects of dl922-947 treatment on IL-8 and CCL2 production by the papillary thyroid carcinoma cell line TPC1." (PMID 26625205, 2016). "Moreover, the modulation of CCL2 by factors such as Canagliflozin, PFHxA, USP15, and Vitamin D further connects its involvement in TC development, particularly in association with papillary thyroid carcinoma and Hashimoto’s thyroiditis." (PMID 39928612, 2025). "In Hu’s study, three genes (ITPR1, CCL2, and CDKN2A) were selected to predict papillary thyroid carcinoma patients’ survival." (PMID 35580861, 2022).
peritoneal effusion (6 papers, 2016 to 2025). "In dogs with SP, the concentrations of glucose, cfDNA, nucleosomes, PCT, CCL2, IL-6, IL-10, and KC-like were significantly different between blood and peritoneal effusion." (PMID 31316998, 2019). "However, in a study of several potential biomarkers in dogs, KC-like did not discriminate between septic peritonitis and nonseptic ascites, as did blood concentrations of CCL2 and peritoneal effusion concentrations of CCL2, IL-6, IL-10 and lactate." (PMID 39272157, 2024).
pneumonitis (6 papers, 2007 to 2022). An inflammatory process affecting the lung parenchyma. "In vivo analysis has shown elevated mRNA levels of CCL2 at two days post-infection with C. trachomatis mouse pneumonitis (MoPn) strain." (PMID 22894815, 2012). "SsRNA stimulation of human leukocytes induced cytokines/chemokines similar to those observed in murine SARS-CoV pneumonitis including IL-1α, IL-1β, IL-6, TNF, CXCL8 (IL-8), CCL2 (MCP-1), CCL3 (MIP-1α), and CCL4 (MIP-1β)." (PMID 23236475, 2012). "Monocyte chemoattractant protein-1 (MCP-1)/CCL2 and interferon-inducible protein-10 (IP-10)/CXCL10 have been reported to be involved in the process of sialadenitis and pneumonitis in MRL/lpr mice." (PMID 17284325, 2007).
renovascular hypertension (6 papers, 2018 to 2024). High blood pressure secondary to renal artery stenosis. "We tested the hypothesis that Ccl2 deficiency protects the stenotic kidney (STK) from development of chronic renal damage in mice with renovascular hypertension due to renal artery stenosis (RAS)." (PMID 29872089, 2018). "The deficiency leads to reduced monocyte infiltration and lower expression of CCR2 and CD206, suggesting that CCL2 is a key mediator of kidney injury in renovascular hypertension." (PMID 39850880, 2024). "In a murine model of renovascular hypertension, we found that tubular epithelial cells in the stenotic kidney strongly expressed Ccl2, a potent monocyte chemoattractant factor, within 24 hours of surgery to establish renal artery stenosis." (PMID 35413089, 2022). "A number of chemokines known to attract mononuclear cells were induced by renovascular hypertension and even more increased in the malignant form of the disease, notably CCL2 and CCL7." (PMID 34528115, 2021). "Previous reports have indicated that renal tubular epithelial cells could act as the initial source of CCL2 in the development of chronic renal damage in a murine renovascular hypertension model." (PMID 31223426, 2019).
scrub typhus (6 papers, 2014 to 2026). Scrub typhus is a rare dust mite-borne infectious disease caused by the Orientia tsutsugamushi bacterium and characterized clinically by an eruptive fever which is potentially serious. "On day 4 post-infection, Karp induced significant elevation of transcriptional inflammatory signatures (Ccl2, Il33, Ifng) and inflammatory gene pathways (Il1, Il6, Tnf, Ifng), the characteristics of severe scrub typhus." (PMID 42112365, 2026).
Senile plaques (6 papers, 2016 to 2025). Senile plaques are extracellular deposits of amyloid in the gray matter of the brain. "Recently studies of human indicate that CCL2 levels are increased in the brains of AD patients, and CCL2 co-localizes with senile plaques." (PMID 26910914, 2016). "Monocyte chemotactic protein 1 (MCP-1)—also known as CC chemokine ligand 2 (CCL2)—was the first chemokine associated with AD and plays a pivotal role in the recruitment and accumulation of immune cells at the level of senile plaques." (PMID 34573867, 2021).